CXCL12 (C-X-C motif chemokine ligand 12)
Diseases named in the same sentence as CXCL12 in open-access papers (continued):
Sharing a sentence is not in itself a finding about the gene and the disease.
pancreatic ductal adenocarcinoma (21 papers, 2011 to 2025). An infiltrating adenocarcinoma that arises from the epithelial cells of the pancreas. "The CXCL12/CXCR4 axis may play an important role in the deproliferative response of pancreatic ductal adenocarcinoma, whereas loss of CXCR4 induces undifferentiated carcinomas with altered pancreatic phenotype without differentiated response." (PMID 34449964, 2021). "CXCR4, activated by its ligand CXCL12 (also known as SDF-1), plays a crucial role in promoting the migration and invasion of tumor cells in pancreatic ductal adenocarcinoma (PDAC)." (PMID 39001498, 2024). "Previous studies have also demonstrated the importance of fibroblast-derived CXCL12 in the evasion of immunosurveillance in pancreatic ductal adenocarcinoma." (PMID 24970800, 2014). "Similarly, in pancreatic ductal adenocarcinoma, iCAFs‐derived CXCL12 mediates immune exclusion by preventing T cell infiltration, contributing to immune checkpoint inhibitor resistance." (PMID 41395115, 2025). "Blocking CXCL12 signalling has been implicated in the success of immune checkpoint inhibitors in preclinical models and a clinical trial of pancreatic ductal adenocarcinoma, suggesting that intratumoural levels of CXCL12 may have implications within the clinical setting of treatment for patients." (PMID 39743376, 2025). "For instance, in pancreatic ductal adenocarcinoma, PDAC, CAF-secreted CXCL12 (SDF-1), has been reported to increase SATB1 expression in tumor cells and to contribute to gemcitabine resistance." (PMID 40940809, 2025). "In total, 14 healthy donors (NHS), 9 patients with pancreatic ductal adenocarcinoma (PDAC), and 9 with Sjogren syndrome (SSj) were recruited as controls and screened for circulating SDF-1/CXCL12 by ELISA." (PMID 34764871, 2021). "In pancreatic ductal adenocarcinoma, FAP-positive CAFs suppressed the effects of anti-PD-L1 treatment through CXCL12/CXCR4 signalling." (PMID 31462002, 2019). "The pancreatic expression of SDF-1/CXCL12 and its receptor CXCR4 was also studied in a subset of IgG4-RD patients with autoimmune pancreatitis (IgG4-RD AIP) and compared to what was observed in the pancreatic ductal adenocarcinoma (PDAC)." (PMID 34764871, 2021). "In pancreatic ductal adenocarcinoma (PDAC), CXCL12 produced by FAP+ CAFs coats tumor cells and excludes T cells; CXCR4 blockade (AMD3100) disrupts this barrier, permits intratumoral CD8+ accumulation, and synergizes with anti-PD-L1." (PMID 40940809, 2025).
Autoimmunity (20 papers, 2011 to 2026). The occurrence of an immune reaction against the organism's own cells or tissues. "Another module-derived gene CXCL12 has been associated with both pre-eclampsia and autoimmunity, further supporting the connection between pregnancy- and disease-related changes." (PMID 34605719, 2022). "The indirect connection of BTK to the disease-associated CXCL12 pathway can be seen by its connection to PLC-γ 2 where a gain-of-function mutation in PLC-γ 2 leads to SLE-like autoimmunity by altering B cell Ca2+ signaling." (PMID 34803999, 2021). "In other words, HA aggravates CNS autoimmunity by amplifying encephalitogenic T-cell responses and suppressing the protective chemokine CXCL12 in CNS tissue." (PMID 38259497, 2023). "CXCL12 levels are raised in individuals with a range of inflammatory illnesses, indicating that CXCL12 plays a role in autoimmunity." (PMID 37858116, 2023). "The basic concept has been that CXCL12 would enhance the development of L-10 producing Tr1-like cells and M2 macrophages and by so doing restrains autoimmunity within the CNS." (PMID 34944943, 2021). "We first applied this technology thirteen years ago when generating stabilized CXCL12-Ig for therapy of autoimmunity within the CNS." (PMID 34944943, 2021). "Our study has expanded the growing list of signaling pathways involved in CXCL12 signaling and should prove a valuable resource for future studies in areas as diverse as autoimmunity, cancer biology, and infectious diseases." (PMID 21949786, 2011). "Long ago we observed that CXCL12 upregulates IL-10 production by macrophages, and T regulatory-1 cells (Tr1) and by so doing restrains the autoimmunity, and may suppress anti-tumor immune reactivity." (PMID 34944943, 2021). "Summary of CXCL12-mediated effects on cells in autoimmunity." (PMID 31507535, 2019). "CD26/DPP4 is a membrane-associated exopeptidase that by engaging inhibitory ligands may limit autoimmunity in mice by regulating Th1 responses, and by hydrolyzing substrates CXCL12 and CCL5." (PMID 31829262, 2019). "In this study, we focused on the CXC α-chemokine Stromal cell Derived Factor-1 (SDF-1)/CXCL12, which together with its main receptor CXCR4, constitutes the chemokine/receptor axis attracting the greatest level of interest in autoimmunity." (PMID 23244336, 2012). "Because chemokines and especially CXCL12 can facilitate decisive crosstalk between B and T cells, notably by recruiting these immune cells in lymphoid and non-lymphoid tissues and organs, the CXCL12/CXCR4 axis received particular attention in autoimmunity." (PMID 34744730, 2021). "The basic rational is that the stabilized form of chemokines that induce Tr1-like cells, among them CXCL12 and CXCL11, could be used for therapy of autoimmunity and GVHD, whereas stabilized CXCL10 would be used for cancer therapy." (PMID 26648938, 2015). "These shared inflammatory pathways highlight the overlapping mechanisms in vitiligo and connective tissue diseases, suggesting that the dysregulation of CXCL12 and CCL5 may serve as a common link, driving autoimmunity and sustained immune activation in these conditions." (PMID 39860439, 2025). "In autoimmunity there are indications that the interaction of CXCR4 and CXCL12 could be important." (PMID 27519689, 2016).
esophageal cancer (20 papers, 2013 to 2025). A primary or metastatic malignant neoplasm involving the esophagus. "The important role of CXCL12 in the invasion and metastasis of esophageal cancer stem cells was also confirmed by loss-of-function and gain-of-function strategies." (PMID 28193907, 2017). "The interaction between CXCL12 and its receptors has been implicated in the progression and metastasis of various cancers, including ovarian, lung, breast, cervical, colon, gastric, and esophageal cancers 117, 119-126." (PMID 39132165, 2024). "While clinical evidence suggested that continuous up-regulation of CXCL12/CXCR4 was significantly associated with poor prognosis in patients with esophageal cancer, but the role and mechanism of CXCL12/CXCR4 in the invasion and metastasis of esophageal cancer has not been reported by far." (PMID 28193907, 2017). "Taken together, our findings suggested that autocrine CXCL12/CXCR4 was one of the major mechanisms underlying the metastatic property of esophageal cancer stem cells through ERK1/2 signaling pathway, and might serve as a therapeutic target for esophageal cancer patients." (PMID 28193907, 2017). "In esophageal cancer, in vitro experiments have demonstrated that the CXCL12/ACKR3 axis activates the STAT3 pathway." (PMID 38920657, 2024). "Studies have revealed that CXCL12 is abnormally elevated in the serum of esophageal cancer patients, particularly those with poorly differentiated tumors." (PMID 37359527, 2023). "Based on these findings, it is inferred that the expression of CXCL12 promotes hematogenous and lymphatic metastasis in esophageal cancer, although the specific mechanism requires further exploration." (PMID 37359527, 2023). "This study found that esophageal cancer stem cells not only autocrine a great amount of CXCL12, but also high expression of its corresponding receptor CXCR4." (PMID 28193907, 2017). "The peptide analog of CXCL12, CTCE-9908, exhibits anti-tumoral effects in in vivo tumor models, including breast, prostate and esophageal cancer, by inhibiting CXCL12-induced primary tumor growth and metastasis." (PMID 28410420, 2017). "That is why we conducted the real-time PCR test to confirm that ECSCs, whether from OE33 cells or samples of esophageal cancer tissues, have significantly high expression of CXCL12; ELISA also confirmed the autocrine secretion of CXCL12 by ECSCs." (PMID 28193907, 2017). "In this study, we found that autocrine CXCL12/CXCR4 was one of the major mechanisms underlying the metastatic property of ECSCs through ERK1/2 signaling pathway, and might serve as a therapeutic target in esophageal cancer patients." (PMID 28193907, 2017). "The knockdown of chemokine CXCL12 also inhibited the expression of EMT-related proteins and the mesenchymal morphology changes of esophageal cancer cells, but the knockdown of C-X-C motif chemokine receptor 4 (CXCR4) had no such effect." (PMID 35264069, 2022). "Inhibition of the STAT3 pathway using AZD9150 weakened the accelerated effects of CXCL12/CXCR7 on the growth and metastasis of esophageal cancer in vitro and in vivo." (PMID 35264069, 2022). "In conclusion, our research revealed that CXCL12/CXCR7 regulates EMT and other malignant processes by activating the STAT3 pathway to accelerate the growth and metastasis of esophageal cancer." (PMID 35264069, 2022). "Here, we investigated the regulatory mechanism of CXCL12/CXCR7 in the growth and metastasis of esophageal cancer." (PMID 35264069, 2022). "Mechanistically, we demonstrated that CXCL12/CXCR4 activated the ERK1/2 pathway and thereby ultimately maintained the characteristics of high-level invasion and metastasis of esophageal cancer stem cells." (PMID 28193907, 2017). "Evidences including the important role of CXCL12/CXCR4 in tumor invasion and metastasis and its strong correlation with the poor prognosis in patients with esophageal cancer have been reported in literature." (PMID 28193907, 2017).
esophageal cancer (continued). "The chemokine CXCL12 and its receptor CXCR4 play a major role in tumor invasion, proliferation and metastasis in different malignant diseases, including esophageal carcinoma, amongst others." (PMID 24074251, 2013). "Moreover, CXCL12-CXCR4 interactions were shown to stimulate the autocrine secretion of CXCL12 and induce cancer invasion and metastasis in CXCR4-positive esophageal cancers." (PMID 37760498, 2023).
metastatic tumors (20 papers, 2010 to 2023). "CXCL12/CXCR4 signaling has been implicated in the development of metastatic disease in PC and anti-chemokine therapies limit the initial establishment of bone metastases in mice models through targeting tumor stromal interactions in bone tumor microenvironment." (PMID 38239314, 2023). "Ongoing work will investigate how CXCL12 signaling shapes overall metabolic plasticity in primary and metastatic tumors, including effects on the metabolism of other molecules, such as lipids." (PMID 35681470, 2022). "A larger dataset including lymph vascular invasion status or IGCCCG classification is needed to reliably assess a potential independent prognostic impact of CXCL12 expression in localised and metastatic disease respectively." (PMID 31412792, 2019). "Many studies do not report the protein expression pattern; nevertheless in our study immunoreactivity to CXCR4 was observed mainly in the cell membrane while CXCL12 appears more often in the cytoplasm of primary and metastatic tumor cells." (PMID 30012106, 2018). "CXCR4 is often overexpressed in metastatic tumors and promotes the migration of invasive cells to tissues where local CXCL12 secretion is increased, such as bone, liver, brain and lung." (PMID 28666461, 2017). "Chemokine (C-X-C motif) receptor 4 (CXCR4) expression increases during progression of PCa and is associated with metastatic disease and poor survival CXCR4 selectively binds to stromal cell-derived factor 1 (SDF-1)/ CXCL12, also overexpressed in PC metastatic tissue compared to normal tissues." (PMID 31718684, 2019). "Patients with metastatic disease and CXCL12 positive primary tumors may need more intense first-line chemotherapy and/or at least a closer post-chemotherapy follow-up." (PMID 31412792, 2019). "Our analysis suggests that patients with metastatic disease and a CXCL12-positive non-seminoma are at higher risk for disease recurrence after first-line chemotherapy and might thus be candidates for more intensive treatment and/or closer follow-up." (PMID 31412792, 2019). "Our present results are consistent with the previous results that the inhibition of the CXCL12-induced CXCR4-mediated signaling suppressed the growth of both primary and metastatic tumors." (PMID 26083776, 2015). "Expression of chemokines and their receptors, such as CXCL12/CXCR4 and CCL21/CCR7, in both primary and metastatic tumors suggest that chemokine receptor-bearing cells actively enter the circulation and home to metastatic sites." (PMID 25909600, 2015). "OS differences were not statistically different between patients with CXCL12 positive or negative tumors for either localized or metastatic disease." (PMID 31412792, 2019). "Expression of the CXCR4 receptor, which is upregulated on cancer cells in both primary and metastatic tumors, mirrors that of CXCL12, suggesting that CXCR4-bearing cancer cells are actively guided by CXCL12 gradients to exit the primary tumor and metastasize to distant organs." (PMID 25909600, 2015). "CXCL12/CXCR4 transactivation of epidermal growth factor family receptors in lipid raft membrane microdomains on cell surface is thought to mediate tumor growth and subsequent development of metastatic disease." (PMID 24472670, 2014).
AIDS (19 papers, 2011 to 2025). A syndrome resulting from the acquired deficiency of cellular immunity caused by the human immunodeficiency virus (HIV). "A SNP has been reported in the 3′-untranslated evolutionarily conserved region of the gene encoding CXCL12 and homozygotes for this SDF1-3′A allele have shown a phenomenal protection against AIDS." (PMID 28178200, 2017).
periodontitis (19 papers, 2016 to 2025). An acute or chronic inflammatory process that affects the tissues that surround and support the teeth. "The LASSO analysis results showed that two overlapping genes (CCDC69 and CXCL12) were the optimal shared diagnostic biomarkers for periodontitis and IgAN." (PMID 36793719, 2023). "We then performed external validation for the diagnostic efficacy of CCDC69 and CXCL12 in the periodontitis dataset GSE10034 and the IgAN dataset GSE73963, and all showed potent predictive performance." (PMID 36793719, 2023). "Importantly, we found that targeting the endothelial CXCL12 signalling pathway in smoking-associated periodontitis reduced the proinflammatory macrophage phenotype, alleviated epithelial inflammation, and reduced alveolar bone resorption." (PMID 40750693, 2025). "Finally, two overlapping genes (CCDC69 and CXCL12) were discovered to be the optimal shared diagnostic biomarkers for periodontitis and IgAN." (PMID 36793719, 2023). "Targeting CXCL12 shows promise in mitigating inflammation and bone resorption in individuals with smoking-induced periodontitis." (PMID 40750693, 2025). "As an important crosstalk gene between IgAN and periodontitis, CXCL12 (CXC chemokine ligand 12) is a potent chemoattractant that belongs to the CXC chemokine family." (PMID 36793719, 2023). "Among these 48 crosstalk genes and the chronic periodontitis-related genes in DisGeNET, C4A, C4B, CXCL12, FCGR3A, IL1B, and MMP3 were shared and identified as the most pivotal candidate links between periodontitis and AD." (PMID 33869630, 2021). "For instance, CXCL12 (the chemokine stromal-cell derived factor-1) was increased in human periodontitis by targeting CXCR4." (PMID 34635105, 2021). "Furthermore, our analysis of cell communication between endothelial and immune cells in individuals with smoking-related periodontitis conditions reveals that endothelial cell-derived CXCL12 influences macrophages by binding to CXCR4." (PMID 40750693, 2025). "Both CCDC69 and CXCL12 were upregulated in periodontitis and IgAN." (PMID 36793719, 2023). "CXCL12 expression in the gingival crevicular fluid of periodontitis patients was shown to be significantly higher than that of healthy subjects, suggesting that it might play a role in enhancing neutrophil migration and further the progression of periodontitis." (PMID 33869630, 2021). "In this study, ROC analysis found that the AUC of CXCL12 was 0.875 for predicting periodontitis and 0.759 for predicting IgAN, and the AUC of CCDC69 was 0.866 for predicting periodontitis and 0.966 for predicting IgAN." (PMID 36793719, 2023). "The SPAG4, CCDC69, KRT10, CXCL12, HPGD, CLDN20 and CCL187 genes were the most important cross-talk genes between periodontitis and IgAN." (PMID 36793719, 2023). "By taking the intersection of WGCNA important module genes and DEGs, we found that the SPAG4, CCDC69, KRT10, CXCL12, HPGD, CLDN20 and CCL187 genes were the most important cross-talk genes between periodontitis and IgAN." (PMID 36793719, 2023). "In this study, CCDC69 and CXCL12 had a significant positive correlation with central memory CD4+ T cells and immature B cells in both periodontitis samples and IgAN samples." (PMID 36793719, 2023). "The further PPI analysis has revealed some of genes play a key role in pathogenesis in periodontitis, including WNT3A, BMP2, CXCL12 and PI3KR2." (PMID 35491409, 2022). "Exploration of available transcriptomic datasets revealed C4A, C4B, CXCL12, FCGR3A, IL1B, and MMP3 as the top candidate molecular linkage genes between periodontitis and AD." (PMID 33869630, 2021). "Six genes C4A, C4B, CXCL12, FCGR3A, IL1B, and MMP3 were identified as the most significant crosstalk genes linking chronic periodontitis and Alzheimer's disease." (PMID 33869630, 2021).
periodontitis (continued). "Indeed, high levels of CCL11, also named Eotaxin-1/C-C motif chemokine 11, CXCL12, also referred to as stromal cell-derived factor-1 (SDF-1) and CCL7, also known as monocyte chemotactic protein-3 (MCP-3) were suggested as biomarkers for periodontitis." (PMID 35048045, 2021). "In silico analysis demonstrates that HBPs may have a role in periodontal disease and can be used for identifying potential drug targets that include chemokines, CXCL12, and proteases, MMP-2 and -9, for regulating periodontitis." (PMID 26821679, 2016). "Therefore, both CXCL12 and CCDC69 have good predictive properties for periodontitis and IgAN." (PMID 36793719, 2023). "Moreover, chemokines such as CXCL8, CXCL10, CXCL12, and CCL5 accumulate in the crevicular fluid of periodontitis patients and their source might be attributed to fibroblasts at least for CXCL2, CXCL3, CXCL8, CXCL9, CXCL10, CXCL12, and CXCL16." (PMID 37762294, 2023). "By taking the intersection of WGCNA important module genes and DEGs, we found that the SPAG4, CCDC69, KRT10, CXCL12, HPGD, CLDN20 and CCL187 genes were the most important cross-talk genes between periodontitis and IgAN, and these genes may be related to kinase regulator activity." (PMID 36793719, 2023).